CSF3R (colony stimulating factor 3 receptor)
Diseases named in the same sentence as CSF3R in open-access papers (continued):
Sharing a sentence is not in itself a finding about the gene and the disease.
tumor (continued). "The number of CD45+ cells infiltrating the tumor was similar in Csf3r−/− and Csf3r+/+ mice." (PMID 31257026, 2019). "G-CSF may also promote tumor progression via CSF3R-coupled JAK/STAT and PI3K/AKT signaling pathways, the epithelial–mesenchymal transition (EMT), and expansion of myeloid-derived suppressor cells (MDSCs), ultimately creating an immunosuppressive microenvironment." (PMID 41009649, 2025). "Tumor-associated neutrophils (TANs) were virtually absent in Csf3r−/− tumors." (PMID 31257026, 2019). "Of which, CSF3R, which is a member of the family of cytokine receptors and may also function in some cell surface adhesion or recognition processes, was reported to be related to tumor growth and metastasis." (PMID 28009993, 2017). "Previous studies have reported that the pro-tumor effects of CSF3 are primarily mediated by neutrophils and myeloid-derived suppressor cells(MDSCs), which are the main populations expressing CSF3R." (PMID 40185722, 2025). "Anti-tumor TAM subsets (CD74 and CD163-CD206 phagocytic TAMs) exhibited high expression of MHCII and CSF3R, and a 3- and 7-fold increase with ACTM-838 treatment, respectively." (PMID 41048107, 2025). "In neutrophil‐1, overexpression of HIF1A enhanced VEGF expression in response to hypoxia, and the activation of CSF3R‐NAMPT‐STAT3 signalling augmented angiogenesis and tumour growth." (PMID 39021279, 2024). "In both tumor and normal lung tissue of all core atlas samples, the neutrophil cluster (FCGR3B, CSF3R, CXCR2, and G0S2) comprised 8,468 cells with overt low mRNA counts." (PMID 36368318, 2022). "In CC, we see shifts in multiple T cell phenotypes, both towards pro-tumor and anti-tumor responses that correlate with CSF3 and CSF3R expression." (PMID 33606788, 2021). "Higher tumor or nodal stages did not demonstrate significant enrichment of CSF3 or CSF3R expression, which was surprising given that smaller studies have found higher expression of both ligand and receptor in higher T and N stage patients." (PMID 33606788, 2021). "In addition, an up-regulation of macrophage receptors involved in cell activation and recruitment (e.g. CD80, CD86, CSF3R, CSF2RB and CD209) was observed 8 hours after treatment possibly indicating an increased presence of activated macrophages in the tumor at this point in time." (PMID 27463372, 2016).
cancer (40 papers, 2007 to 2025). A tumor composed of atypical neoplastic, often pleomorphic cells that invade other tissues. "The analysis of these mutational landscapes identified both novel and known somatic mutations in known cancer genes and also in novel genes such as CSF3R in B-ALL patients." (PMID 34573308, 2021). "CSF3R was found to be associated with cancer-associated pathways, and further studies could determine whether CSF3R methylation values can be used as a prognostic marker." (PMID 38791003, 2024). "Exemplary cases include ncORFs in the cancer hallmark genes CREBBP, CRTC1, CSF3R, FGFR2, IKZF1 and MAP2K2 with peptide support in all but two of the analyzed cancer types." (PMID 37275273, 2023). "In comparison to normal tissues, Nos2, Hgf, Lama1, Csf3r, Csf2rb2, Col4a1, Col4a2, Adcy2, Adcy4, Gstm3 and Gstm6 were identified as the most significant genes in cancer pathways." (PMID 37774039, 2023). "Some of them were cancer-type specific (such as CSF3R), while some others (such as LZTR1 and ERCC4) showed consistent alterations across multiple cancers." (PMID 38067392, 2023). "Only three genes—ACTB, CSF3R, and GATA2—were identified in both the DEA and mutational analysis, which highlights their possible significance in cancer and disease development." (PMID 36497424, 2022). "Higher expression of CSF3R in both CC and RC was found to correlate strongly with higher scores using the “estimation of stromal and immune cells in malignant tumor tissues using expression data” (ESTIMATE) analysis." (PMID 33606788, 2021). "Of the 34 validated mutations that were significantly enriched in the lung metastases, 17 were predicted to impact protein function (SIFT41 and PolyPhen42), and four fell in cancer genes (CSF3R_Q250L, CDH11_A683S, GRIN2A_S752R, and CDK8_H235Y)." (PMID 30498242, 2018). "In addition, several well-known PID-related genes are recognized as cancer-predisposing genes, including those found in immune dysregulation (e.g., ITK, KRAS), combined immunodeficiencies (e.g., JAK3, RECQL4) and phagocytic disorders (e.g., CDKN2A, CSF3R)." (PMID 36497424, 2022). "Our results evidenced that the expression of cancer stem cell surface markers, including EPCAM, CSF3R, CD34, CD96 and ENG, were significantly different." (PMID 38977778, 2024). "We explored the potential mechanism of GCSF (CSF3), GCSFR (CSF3R) and STAT3 in the pathogenesis of GBM from the dataset of patient samples of the TCGA Pan-Cancer Atlas database with the respective genetic alterations of GCSF (CSF3) 1.7%, GSCFR (CSF3R) 2.1% and STAT3 1.7% respectively." (PMID 38538691, 2024). "Interestingly, both cancers showed significant correlations of formyl peptide receptors FPR1 and FPR2 with CSF3 and CSF3R." (PMID 33606788, 2021). "As the mechanisms of action of the CSF3R gene in cancer cells are still not well defined, it may be only part of a pathway in which multiple mechanisms interact with an unfavorable prognosis as the final result." (PMID 36982406, 2023).
infection (29 papers, 2010 to 2025). The state of being infected such as from the introduction of a foreign agent such as serum, vaccine, antigenic substance or organism. "The role of G-CSF and G-CSFR in regulating blood neutrophil counts was clearly demonstrated in Csf3-/- (G-CSF deficient) and Csf3r-/- (G-CSFR deficient) mice in response to an infection." (PMID 36618429, 2022). "Signaling by CSF3 through the CSF3R contributes in an important manner to neutrophil homeostasis, but especially in the context of inflammation, infection and their respective resolution." (PMID 41154433, 2025). "Knockdown of HMGB1 expression was confirmed by Western blot analyses, which contributed to the upregulation of mRNA level of the granulocytic differentiation markers (CD11b, MPO, and CSF3R) as compared with the lenti-ctrl infection." (PMID 33128580, 2021). "For example, a cytokine receptor (CSF3R) and three chemokines (CXCL8, CXCL14, CCL20) responsible for leukocyte trafficking were upregulated during infection only in birds from less-tolerant populations." (PMID 37294834, 2023). "Their involvement ranges from serving as co-receptors for cell entry (CCR1 and CCBP2), mediating trans-infection (DARC), activating immune cells (CD97) to inducing viral production from latently infected cells (CSF3R, TNFRSF3 and CD2)." (PMID 20967291, 2010). "This difference was not due to a different pathogen burden following infection establishment in the face of lower basal neutrophil abundance, since csf3r knockdown did not alter fungal survival/proliferation as reflected by 24 hours post infection (hpi) CFU numbers." (PMID 29883484, 2018).
bacterial infection (7 papers, 2018 to 2025). "The RIP-qPCR results confirmed the direct binding of ALKBH5 to the CSF3R mRNA, and the binding strength declined upon bacterial infection, accounting for the decrease in G-CSFR expression on bacteria-infected neutrophils." (PMID 38114747, 2024). "The RNA-seq data showed that ALKBH5 deletion significantly decreased the transcript level of CSF3R in both mouse and human neutrophils upon bacterial infection." (PMID 38114747, 2024). "However, during bacterial infection, the binding affinity of ALKBH5 to CSF3R mRNA decreases, causing downregulation of G-CSFR and further impairing mobilization." (PMID 41562066, 2025). "Interestingly, the amount of ALKBH5 bound to the CSF3R mRNA was lower during bacterial infection than under physiological conditions." (PMID 38114747, 2024). "Furthermore, G-CSFR expression is downregulated in neutrophils upon bacterial infection because of decreased binding of ALKBH5 to the CSF3R mRNA." (PMID 38114747, 2024). "Moreover, deletion of ALKBH5 significantly decreased the level of CSF3R mRNA in dHL-60 human neutrophils upon bacterial infection and LPS stimulation." (PMID 38114747, 2024). "The strength of the host defense inflammatory response during bacterial infection is directly related to CSF3 receptor (CSF3R, or CD114/G-CSFR) signaling." (PMID 37888548, 2023).
hematological cancer (3 papers, 2022 to 2025). "Given the rarity of CSF3R mutations in other hematologic cancers, they are considered diagnostic features in patients with CNL and aCML." (PMID 38992589, 2024). "In addition to the important role played by CSF3R mutations in hematological cancers, CSF3R signaling contributes to oncogenesis by other mechanisms including when the CSF3R gene is not mutated." (PMID 41154433, 2025). "For example, in hematological cancers SRSF2 mutations have been shown to increase levels of a normally minor CSF3R transcript encoding a truncated V684Afs*34 CSF3R isoform shown to inhibit differentiation." (PMID 41154433, 2025).
hematological malignancies (3 papers, 2021 to 2025). "An increasing number of CSF3R gene mutations and variants have been identified in hematological malignancies and other disorders." (PMID 41154433, 2025). "However, disruption of this exquisite system by CSF3R mutations can result in hematological malignancies and other diseases." (PMID 41154433, 2025). "This allowed us to identify novel SNVs in genes previously reported as mutated in ALL or other hematological malignancies: CREBBP, CSF3R and DUX4." (PMID 41333018, 2025).
head and neck tumors (1 paper, 2023). "We identified infiltrating neutrophils in head and neck tumors by selecting the myeloid cells with the highest expression of CSF3R (17% of myeloid cells, 1.15% of CD45+ cells) in silico, similar to what was used to define neutrophils in CD45+ cells in a recent myeloid lung cancer atlas." (PMID 38022639, 2023).
CSF3R also shares sentences with these, for which no sentence is quoted: bladder cancer (6 papers); ovarian carcinoma (6); colitis (5); colon carcinoma (5); gastric cancer (5); myeloid leukemia (5); neuroblastoma (5); pancreatic cancer (4); Cerebral ischemia (3); GI tumor (3); ischemia (3); multiple myeloma (3); pneumonia (3); actinic keratosis (2); Alzheimer disease (2); amyotrophic lateral sclerosis (2); Arthritis (2); Bowen’s disease (2); essential thrombocythemia (2); liver disease (2); polycythemia vera (2); primary myelofibrosis (2); rheumatoid arthritis (2); small cell lung carcinoma (2); Stroke (2); Thrombocytosis (2); vasculitis (2); acquired immunodeficiency syndrome (1); alcohol hepatitis (1); alcoholic liver diseases (1).
A further 79 diseases each share a sentence with CSF3R in 1 paper.